TGFBR2 (transforming growth factor beta receptor 2)
Description:
Transmembrane serine/threonine kinase forming with the TGF-beta type I serine/threonine kinase receptor, TGFBR1, the non-promiscuous receptor for the TGF-beta cytokines TGFB1, TGFB2 and TGFB3. Transduces the TGFB1, TGFB2 and TGFB3 signal from the cell surface to the cytoplasm and thus regulates a plethora of physiological and pathological processes including cell cycle arrest in epithelial and hematopoietic cells, control of mesenchymal cell proliferation and differentiation, wound healing, extracellular matrix production, immunosuppression and carcinogenesis. The formation of the receptor complex composed of 2 TGFBR1 and 2 TGFBR2 molecules symmetrically bound to the cytokine dimer results in the phosphorylation and activation of TGFBR1 by the constitutively active TGFBR2. Activated TGFBR1 phosphorylates SMAD2 which dissociates from the receptor and interacts with SMAD4. The SMAD2-SMAD4 complex is subsequently translocated to the nucleus where it modulates the transcription of the TGF-beta-regulated genes. This constitutes the canonical SMAD-dependent TGF-beta signaling cascade. Also involved in non-canonical, SMAD-independent TGF-beta signaling pathways. [Isoform 1]: Has transforming growth factor beta-activated receptor activity. [Isoform 2]: Has transforming growth factor beta-activated receptor activity. [Isoform 3]: Binds TGFB1, TGFB2 and TGFB3 in the picomolar affinity range without the participation of additional receptors. Blocks activation of SMAD2 and SMAD3 by TGFB1.
Synonyms: TGFR-2; TbetaR-II; TBRII; TBR-ii; AAT3; FAA3; LDS1B; LDS2; LDS2B; MFS2; RIIC; TAAD2; TGFbeta-RII
Tractability: Small molecule: a structure with a bound ligand is known; a high-quality ligand is known; it belongs to a druggable protein family. Antibody: UniProt places it where antibodies can reach, with high confidence; its Gene Ontology location is reachable by antibodies, with high confidence; UniProt predicts a signal peptide or a membrane-spanning region; the Human Protein Atlas places it where antibodies can reach. PROTAC: ubiquitination databases record sites on it; a small molecule that binds it is known.
Target class: Kinase; TKL protein kinase STKR family; Protein Kinase; Enzyme; TKL protein kinase group; TKL protein kinase STKR Type 2 subfamily
Safety:
Unwanted effects reported when the protein is acted on. In parentheses: how it was acted on, where the effect was seen, and who reports it.
diarrhea (source: ClinPGx)
Gene: Protein-coding gene on chromosome 3 (30,606,478 to 30,694,249, forward strand). Ensembl gene ENSG00000163513.
Subcellular location: Cell membrane; Membrane raft; Secreted (Isoform 3)
Subcellular location (Human Protein Atlas): Plasma membrane; Predicted to be secreted
Pathways (Reactome):
Disease: SMAD2/3 Phosphorylation Motif Mutants in Cancer; TGFBR1 KD Mutants in Cancer; TGFBR1 LBD Mutants in Cancer; TGFBR2 Kinase Domain Mutants in Cancer; TGFBR2 MSI Frameshift Mutants in Cancer
Signal Transduction: Downregulation of TGF-beta receptor signaling; TGF-beta receptor signaling activates SMADs; TGF-beta receptor signaling in EMT (epithelial to mesenchymal transition); TGFBR3 regulates TGF-beta signaling
Metabolism of proteins: UCH proteinases
Gene Ontology:
Molecular function: glycosaminoglycan binding; molecular adaptor activity; protein binding; SMAD binding; transforming growth factor beta binding; transforming growth factor beta receptor activity; transforming growth factor beta receptor activity, type II; transmembrane receptor protein serine/threonine kinase activity; type I transforming growth factor beta receptor binding; activin binding; activin receptor activity, type I; protein serine/threonine kinase activity; ATP binding; kinase activator activity; metal ion binding; protein kinase activity; signaling receptor activity
Biological process: aorta morphogenesis; aortic valve morphogenesis; apoptotic process; artery morphogenesis; epithelial to mesenchymal transition; positive regulation of CD4-positive, alpha-beta T cell proliferation; positive regulation of epithelial to mesenchymal transition; positive regulation of reactive oxygen species metabolic process; positive regulation of SMAD protein signal transduction; regulation of stem cell differentiation; response to cholesterol; response to xenobiotic stimulus; roof of mouth development; transforming growth factor beta receptor signaling pathway; activin receptor signaling pathway; atrioventricular valve morphogenesis; blood vessel development; brain development; branching involved in blood vessel morphogenesis; cardiac left ventricle morphogenesis; cell proliferation involved in endocardial cushion morphogenesis; cellular response to growth factor stimulus; embryonic cranial skeleton morphogenesis; embryonic hemopoiesis; endocardial cushion fusion; and 30 more
Cellular component: caveola; external side of plasma membrane; extracellular region; membrane; membrane raft; plasma membrane; receptor complex; transforming growth factor beta ligand-receptor complex; activin receptor complex; cytosol; cell surface
Genetic constraint (gnomAD): Loss-of-function variants: 18 observed, 50.22 expected, observed/expected ratio (o/e) 0.36, 90% interval 0.25 to 0.53. The upper end of that interval is the gene's LOEUF score, 0.53, which puts it in group 2 of 6, group 1 being the genes least tolerant of losing a copy. Missense variants: 525 observed, 745.29 expected, observed/expected ratio (o/e) 0.7, 90% interval 0.65 to 0.76. Synonymous variants: 282 observed, 285.55 expected, observed/expected ratio (o/e) 0.99, 90% interval 0.89 to 1.09.
Gene-disease validity (ClinGen):
ClinGen rates the evidence that TGFBR2 causes each of these diseases.
Loeys-Dietz syndrome 2 (autosomal dominant): Definitive. A rare autosomal dominant inherited disorder of connective tissue caused by mutations in either the TGFBR1 or TGFBR2 gene.
Cancer hallmarks: suppression of growth (promotes); invasion and metastasis (suppresses)
Homologues: Orthologues: macaque TGFBR2 (99% identical), chimpanzee TGFBR2 (98% identical), rabbit TGFBR2 (95% identical), dog TGFBR2 (94% identical), guinea pig TGFBR2 (93% identical), mouse Tgfbr2 (92% identical), rat Tgfbr2 (91% identical), pig TGFBR2 (89% identical), tropical clawed frog tgfbr2 (69% identical), zebrafish tgfbr2b (66% identical), zebrafish tgfbr2a (52% identical). Paralogues in human: ACVR2A (31% identical), ACVR2B (31% identical), BMPR2 (29% identical), TGFBR1 (27% identical), ACVR1B (26% identical), ACVR1C (25% identical), ACVRL1 (25% identical), ACVR1 (25% identical), BMPR1B (24% identical), BMPR1A (24% identical), AMHR2 (22% identical).
Diseases named in the same sentence as TGFBR2 in open-access papers:
TGFBR2 is named in the same sentence as 337 diseases in open-access papers, as found by Europe PMC text mining. Sharing a sentence is not in itself a finding about the gene and the disease. The quoted sentences say what the papers report.
breast cancer (121 papers, 2004 to 2026). A primary or metastatic malignant neoplasm involving the breast. "The majority of studies exploring the clinical significance of TGFBR2 mutations are in the context of breast cancer, where high expression of TGFBR2 is associated with tumor metastasis and response to chemotherapy." (PMID 29383146, 2017). "When analyzing clinical, in vitro and in vivo data, our studies collectively support the notion that TGFBR2 expression in CAFs is linked to prognostic features and key tumor properties in breast cancer." (PMID 26682269, 2015). "TGFBR2 has been identified as a susceptibility locus for breast cancer risk and its expression in cancer-associated fibroblasts was found to be a prognostic marker for pre-menopausal breast cancer." (PMID 25849327, 2015). "They lay in a different LD block from that of the reported breast cancer risk-associated SNPs that led to the identification of TGFBR2 as a breast cancer susceptibility locus." (PMID 25849327, 2015). "Several authors, have associated the TGFBR2-875G>A polymorphism with a decreased risk for gastric cancer, esophageal squamous cell carcinoma, breast cancer, and lymph node metastasis, especially in the Asian population." (PMID 23951322, 2013). "The inactivation of TGFBR2 gene in mouse fibroblasts has been associated with prostate intraepithelial neoplasia and invasive squamous cell carcinoma of forestomach development, and this alteration can also promote growth and invasion of co-transplanted breast cancer cells." (PMID 23951322, 2013). "S1P treatment enhanced exosome release from breast cancer cells, with increased levels of TGFBR2 detected on the exosome surface." (PMID 41872131, 2026). "The role of miRNA-145 has been highlighted in the development of metastasis and tumor proliferation in breast cancer cells by upregulating the expression of Transforming Growth Factor-beta Receptor 2 (TGFBR2)." (PMID 37047783, 2023). "BMP2, BMP4, GDF11 and TGFBR2 had relatively higher levels in bone metastases of breast cancer while BMP5, BMP7, BMPR2, BMPR1A and ACVR2A presented lower expression in the bone metastases, in the E-MTAB-4003 dataset." (PMID 37333824, 2023). "We also discovered that mammary tumors generated by Tgfbr2 KO cells produced significantly less metastatic nodules in the lung when compared with the tumors initiated by control cells." (PMID 35236825, 2022). "Through analysis of the TIMER database, we found that the expression of TGFB1, TGFBR1, and TGFBR2 are correlated with the infiltration levels of various immune cells in breast cancer." (PMID 34485309, 2021). "MiR-155 was expressed at a high level in breast cancer tissues compared with paired normal tissues, while TGFBR2 was expressed at a low level." (PMID 34299149, 2021). "Collectively, our results indicate that ALG3 promotes radioresistance and CSC-like traits by activating TGF-β signaling dependent on glycosylation of TGFBR2 in breast cancer." (PMID 33931075, 2021). "Using a combination of proteomics-based kinome profiling, transcriptomic analyses and molecular approaches, we identified TGFBR2 as a critical downstream target of SOX4 in basal-like breast-cancer cell lines." (PMID 33837205, 2021). "Second, detailed investigations on the genes that make up the lncRNA ADAMTS9-AS1/miR-301b-3p/TGFBR2 axis can further understand the mechanism of lncRNA ADAMTS9-AS1 inhibiting breast cancer progression." (PMID 34900984, 2021). "Elevated expression levels of TGFBR2 has been reported in a doxorubicin-resistant breast cancer MCF-7 cell line when compared to a sensitive MCF-7 cell line." (PMID 33961622, 2021). "Altogether, ADAMTS9-AS1 restrained the proliferation and invasion of breast cancer via stimulating the level of TGFBR2 through miR-301b-3p." (PMID 34900984, 2021). "The relationship between the expression levels of TGFBR1 and TGFBR2 and immune cell infiltration in different breast cancer subtypes was also analyzed." (PMID 34485309, 2021).
breast cancer (continued). "The expression level of TGFBR2 was positively correlated with the infiltration level of multiple immune cells in different subtypes of breast cancer." (PMID 34485309, 2021). "Among the EMT genes analyzed here, only TGFBR2 is a bona fide NF-Y target, as determined in breast cancer cells." (PMID 31506469, 2019). "Positive correlation of MET with TGFBR2 gene expression was also observed in breast cancer tissue using the breast cancer TCGA dataset and, at the protein level, in 801 breast cancer specimens." (PMID 30004628, 2018). "To this end, we activated MET and TGFβ signaling pathways with HGF and TGFβ1, respectively, and tested their influence on TGFBR2 or MET expression in the model cell line MCF10A as well as in basal‐like breast cancer cell lines HS578T and HCC1143." (PMID 30004628, 2018). "In this study, we performed a genomewide correlation analysis of TGFBR2 in a panel of 51 breast cancer cell lines to identify genes which are coregulated with TGFBR2 and to test their impact on cell migration." (PMID 30004628, 2018). "In this study, we performed genomewide correlation analysis of TGFBR2 expression in a panel of 51 breast cancer cell lines and identified that MET is coregulated with TGFBR2." (PMID 30004628, 2018). "In a previous study, we have identified a tumor‐suppressive function of the miR‐520/miR373 family by targeting TGFBR2 in breast cancer cells." (PMID 30004628, 2018). "To this end, we bioinformatically searched for putative transcription factor binding sites in the MET promoter and combined this with an analysis of genes that are coexpressed with either TGFBR2 or MET in breast cancer cell lines." (PMID 30004628, 2018). "Correlation of ETS1 with MET and TGFBR2 was observed as well in breast cancer tissue using the TCGA breast cancer dataset." (PMID 30004628, 2018). "There, we identified TGFBR2 as being higher expressed in basal‐like compared to luminal as well as higher in ER‐negative compared to ER‐positive breast cancer cell lines." (PMID 30004628, 2018). "To further elaborate on the function of TGFBR2 within subtypes of human breast cancer, we initially analyzed a gene expression dataset from 51 breast cancer cell lines." (PMID 30004628, 2018). "To validate these findings, we measured surface expression of TGFBR2 at the protein level in several breast cancer cell lines confirming elevated expression in basal‐like compared to luminal cell lines." (PMID 30004628, 2018). "C‐ets‐1 was the top candidate as this transcription factor has previously been described to synergize with SMAD3 and its expression also correlated the most with expression of TGFBR2 as well as of MET in breast cancer cell lines." (PMID 30004628, 2018). "It has been shown that TGFβ1 directly acts on the basal‐like breast tumor cell line MDA‐MB‐231 and that this drives metastatic processes of breast cancer cells by its binding to TGFBR2." (PMID 30004628, 2018). "TGFBR2 and TGFB1 are considered putative targets of miR-21 that cause metastasis and patient poor prognosis in breast cancer." (PMID 28793339, 2017). "More specifically, TGFBR1 and FGFR1 in combination with highly expressed E2F1 induce the most invasive phenotype in bladder cancer, whereas in breast cancer, it is the combined action of TGFBR2, EGFR, and E2F1 that triggers high levels of invasiveness." (PMID 28775339, 2017). "On the gene level, in addition to TGFBR2 and CCND1, IL5 and GM-CSF showed the strongest associations with overall breast cancer risk (p value = 1.0 × 10−3 and 7.0 × 10−3, respectively)." (PMID 26621531, 2016). "TGFBR2 and CCND1 showed significant associations with overall breast cancer risk (p value <10−6 and 3.0 × 10−4, respectively)." (PMID 26621531, 2016).
breast cancer (continued). "Furthermore, previous association studies have identified susceptibility alleles for breast cancer in two genes, TGFBR2 (transforming growth factor beta receptor II) and CCND1 (cyclin D1), which may be involved in immune regulation in cancer patients, including those with breast cancer." (PMID 26621531, 2016). "Blockade of TGFβ signaling in CAFs, either through application of a chemical inhibitor or shRNA-induced knockdown of TGFBR2, resulted in increased cell growth and survival of breast cancer cells." (PMID 26682269, 2015). "Lastly, analysis of human breast cancer transcriptome databases demonstrated a significant correlation between decreased TGFBR2 and increased VEGFA gene expression similar to what was observed in the mouse models." (PMID 25280532, 2014). "In the one exception, a TGF-β signature reflecting basal gene expression differences between wild-type and TGFBR2 knockout mouse mammary tumor cells weakly correlated with good outcome in ER+ breast cancers." (PMID 24890385, 2014). "Deletion of the type II TGF-β receptor gene (Tgfbr2) in mammary carcinomas results in the recruitment of Gr-1+CD11b+ MDSCs that directly promoted tumor metastasis through enhanced metalloproteinase and TGF-β production." (PMID 21943203, 2011). "Several studies have demonstrated that tumor cell autonomous genetic inactivation of the TGF-β signaling pathway by knock-down of TGFBR2 or SMAD4 reduced the ability of MDA-MB-231 human basal-like breast cancer cells to metastasize to bone." (PMID 20504320, 2010). "Given that our data identifies SOX4 and SMARCA4 as key modulators of TGFBR2 expression and PI3K activity in basal-like breast cancer, it remains to be determined if aberrant TGFBR2 activity can also regulate a similar resistance mechanism to PI3K-family inhibitors in TNBC patients." (PMID 33837205, 2021). "Similarly, in breast cancer, autocrine activation of TGFBR2 expression in response to chemotherapy has been reported to regulate proliferation of breast-cancer stem cell populations and contribute to tumor recurrence." (PMID 33837205, 2021). "Our results suggest that ALG3 may serve as a potential radiosensitive marker, and an effective target to decrease radioresistance by regulating glycosylation of TGFBR2 in breast cancer." (PMID 33931075, 2021). "Here, inhibiting the expression of TGFBR2 could weaken the tumor suppressor effect of ADAMTS9-AS1, suggesting that TGFBR2 was an inhibitor in breast cancer, which is similar to the results of previous studies." (PMID 34900984, 2021). "Luciferase assay exerted that TGFBR2 was the direct target of miR-155, suggesting that miR-155 might promote breast cancer progression through the down-regulation of TGFBR2." (PMID 34299149, 2021). "ADAMTS9-AS1/miR-301b-3p/TGFBR2 regulatory network may provide a more effective clinical treatment strategy for breast cancer patients." (PMID 34900984, 2021). "However, only inhibiting TGFBR2 in the vector breast cancer cells (vector +LY2109761) exhibited little effect on the surviving fraction compared with the vector breast cancer cells." (PMID 33931075, 2021). "Next, we measured TGFBR2 expression at the protein level in a set of 801 tissue samples of a prospective breast cancer cohort to investigate on TGFBR2 expression in different breast cancer subtypes in vivo." (PMID 30004628, 2018). "We hypothesized that genes which are coexpressed with TGFBR2 could be involved in TGFβ‐mediated progression of breast cancer." (PMID 30004628, 2018). "The hepatocyte growth factor receptor (MET) was among the top significant genes positively correlating with TGFBR2 expression, which could be validated using an independent dataset of breast cancer cell lines." (PMID 30004628, 2018). "MET was one of the top positively correlated genes with TGFBR2 in these breast cancer cell lines." (PMID 30004628, 2018).